BCL2 (BCL2 apoptosis regulator)
Diseases named in the same sentence as BCL2 in open-access papers (continued):
Sharing a sentence is not in itself a finding about the gene and the disease.
leukemia (continued). "In leukemia cells, KLF4 upregulated Bax and downregulated Bcl-2 to induce cell apoptosis, potentially through binding to the sites which correspond to the promoters of Bcl-2 and Bax." (PMID 29848383, 2018). "In a mouse model of adult T cell leukemia driven by HTLV1, potent anti-leukemia effects were seen when ruxolitinib was combined with navitoclax, an inhibitor of BCL-xL and BCL-2." (PMID 29854301, 2018). "Conversely, another study found that treatment of leukemia B cells with NSC-23766, an inhibitor of activated Rac1, enhanced the capacity of Bcl-2 antagonists to induce apoptosis." (PMID 29872501, 2018). "Previous studies indicate downregulation of Bcl-2 in the presence of DATS in human pancreatic, epithelial ovarian, leukemia, lung, breast, and prostate cancer cell lines." (PMID 28852876, 2017). "BCL2 is a crucial anti-apoptotic gene and its role in MLL-AF9 driven leukemia has already been investigated." (PMID 29240787, 2017). "Selective inhibition of cell viability and BCL2 expression in leukaemia cells harboring MLL fusions was observed with the BET bromodomain inhibitor, I-BET151, in contrast to leukaemia cells with alternate oncogenic drivers." (PMID 28653617, 2017). "Quercetin can promote the pro-apoptotic gene (Bax), enhance the anti-apoptotic gene (Bcl-2 and ERK) in leukemia cells, and activate caspase in osteosarcoma and oral cavity cancer cells." (PMID 28583139, 2017). "Further work has shown that miR-15a and miR-16-1 act as tumor suppressors and when decreased lead to increased levels of BCL2, CCNDI, and WNT3A in prostate cancer, increased BCL2 in Chronic Lymphocytic Leukemia, and increased IGSF4 in leukemia." (PMID 27231010, 2016). "Irrespective of the expression of anti-apoptotic BCL-2 family members, the re-programmed p185+ B-ALL cells in which endogenous MCL-1 was replaced by human BCL-2, BCL-XL, BCL-W, MCL-1, or BFL-1 all succumbed to a fatal leukemia with a similar kinetic." (PMID 26862853, 2016). "Thus, placing the ETV6/RUNX1 transgene under control of the Cd19 promoter may be too late to allow for B cell progenitor leukemia development when combined with BCL2 overexpression, but still allowing to promote autoimmune mature B cell abnormalities that aggravate glomerulonephritis." (PMID 26919255, 2016). "CCI-007 altered the characteristic MLL-r gene expression signature in sensitive cells with downregulation of the expression of HOXA9, MEIS1, CMYC and BCL2, important drivers in MLL-r leukemia, within a few hours of treatment." (PMID 27317766, 2016). "MLL-r leukemia is characterised by deregulated gene expression that reportedly entails increased expression levels of HOXA9, MEIS1, CMYC and BCL2, which have been suggested to play important roles in MLL-r leukemia cell survival." (PMID 27317766, 2016). "For this purpose we employed 10E1-CEM (Bcl-2 overexpressing cells) and R5-CEM cells, both derived from the human leukemia CEM native cell line and resistant to antineoplastic drug 4-HPR, among others." (PMID 26688757, 2015). "sgRNA can be easily taken up by cultured cells without any transfection reagents, and naked sgRNAs targeting Bcl2 or WT1 mRNA can reduce the mRNA level and the amount of protein as well as inducing apoptosis of leukemia cells." (PMID 25437003, 2014). "In U937 leukemia cells treated with MG132 or MG132 + DOX, the behavior is comparable; Bcl-2 and Bcl-XL antiapoptotic proteins are significantly reduced in comparison with those of the UCG and the DOX-treated group (p <0.05)." (PMID 24495648, 2014). "All mice that received Bcl-2+/+ cells transduced with HoxA9/Meis1 or MLL-AF9 developed rapid and aggressive leukemia with an average latency of 40 days." (PMID 24177192, 2013).
leukemia (continued). "Expression levels of BCL2 and BCL2L12 were altered during apoptosis induced by widely used chemotherapeutic drugs in human leukemia cells." (PMID 21941553, 2012). "In leukemia cell line HL-60/VCR miR-138 was demonstrated to significantly down-regulate the expression of P-glycoprotein, Bcl-2, and the transcription of the multidrug resistance gene 1 (MDR1)." (PMID 22954303, 2012). "The most prominent anti-apoptotic bcl-2 family members, including bcl-2 (B-cell CLL/lymphoma 2), bcl-XL (BCL2L1) and mcl-1 (myeloid cell leukemia 1; BCL2L3), were originally identified and found to be over-expressed in leukemia cells." (PMID 20105315, 2010). "Combining JAK2 inhibitors with BCL-2 inhibitors such as venetoclax could synergistically enhance leukemia cell death by both disrupting survival signaling (via JAK2 inhibition) and promoting apoptosis (via BCL-2 inhibition)." (PMID 40486651, 2025). "Nevertheless, given the poor prognosis and high relapse rate, patients with NUP98r leukemia may benefit from FLT3 inhibitors, BCL2 inhibitors, and CDK4/6 inhibitors, as well as hematopoietic stem cell transplantation." (PMID 40264981, 2025). "Notably, both 17C7 and 20F2 efficiently reduced leukemia burden in PDX model engrafted with pt#28, who had progressed after multiple previous treatments, including Bcl-2 inhibitor venetoclax." (PMID 38167704, 2024). "BCL-2 expression is high in AML, including in leukemia stem cells (LSCs)." (PMID 36629738, 2023). "However, BCL2 and HOXA9 overexpression inhibited miR-182-induced anti-leukemia activity to some extent, suggesting that there were other targets regulated by miR-182 in AML." (PMID 36593968, 2023). "Besides VEN, several newly developed BCL-2 inhibitors are currently in various stages of investigation in AML and other leukemia models." (PMID 37065864, 2023). "In SUP-T1 cells, apart from downregulation of the known BRD4 targets like Myc, Bcl-2, Bcl-XL, and Mcl-1, treatment with ARV-825 substantially decreased the expression of key molecules involved in leukemia persistence, such as HES1 (a direct target of Notch1), PI3K/AKT pathway proteins, and CD44." (PMID 35173274, 2022). "HSP90 promotes the survival of leukemia cells by binding to APAF-1 and BCL-2." (PMID 36139353, 2022). "Indeed, MRX-2843 synergized with the BCL-2 inhibitor venetoclax in two ETP-ALL cell lines and provided increased anti-leukemia activity against ETP-ALL cells compared with either of the drugs alone." (PMID 36551626, 2022). "Methyltransferase 3(METTL3) increased the translation of downstream leukemia-related genes, such as MYC, BCL2, and PTEN mRNA, in an m6A-dependent manner, and depletion of METTL3 blocked proliferation, induced differentiation, and apoptosis in immunodeficient recipient mice." (PMID 35865470, 2022). "In leukemia, some studies displayed a negative correlation between m6A and apoptosis—Bcl-2 overexpression evoked by FTO and ALKBH5 upregulation fights against apoptosis, resulting in resistance of leukemia cells to tyrosine kinase inhibitors (TKIs)." (PMID 35090469, 2022). "For example, punicalagin exerts the cytotoxic effect by suppressing proliferation and promoting apoptosis and autophagy by activating the caspase cascade, altering Bax and Bcl-2, and regulating autophagy via mTOR/ULK1 signaling in human NB4 and MOLT-4 leukemia cell lines." (PMID 35745713, 2022). "We also clarified that its leukaemia-promoting effects might function through decreased BAX and cleaved caspase-3 and upregulated bcl-2 levels." (PMID 35534496, 2022). "Endogenous BCL2 and SOX4 support the initiation and maintenance of leukemia." (PMID 34310280, 2021). "Although DT2216 is very useful for the treatment of some BCL-xL-dependent T-cell acute lymphoblastic leukemia and T-cell lymphoma, it has a limited effect on other leukemias and most solid tumors unless combined with ABT199 (venetoclax, a selective BCL-2 inhibitor) or chemotherapy." (PMID 34824248, 2021).
leukemia (continued). "Among the HOXA9 target genes, BCL2 and SOX4 synergistically induced leukemia with MYC." (PMID 34310280, 2021). "Indeed, co-expression of HOXA9, BCL2, or SOX4 promoted MYC-mediated leukemogenesis, while MYC alone was insufficient to induce leukemia in vivo." (PMID 34310280, 2021). "Similarly, researchers found that quiescent human leukemia stem cells (LSCs) are highly reliant on B-cell lymphoma 2 (BCL-2)-dependent oxidative phosphorylation; using BCL-2 inhibitors can selectively eradicate quiescent LSCs." (PMID 34685686, 2021). "Indeed, VEGF-facilitated expression of anti-apoptotic proteins, BCL-2, MCL-1 or XIAP, and activation of the PI3K/AKT survival pathway protected colorectal cancer, breast cancer or leukaemia cells from apoptosis." (PMID 34829672, 2021). "Nevertheless, the first attempts to target BCL-2 with the antisense nucleotides G3139 in leukemia models were not fully successful, due to the long half-life of the BCL-2 protein." (PMID 34830763, 2021). "For instance, in leukemia, HOMER3 inhibits expression of Bcl2 thus influencing the cell cycle." (PMID 33969375, 2021). "This is because these leukemias and solid tumors depend on both BCL-xL and BCL-2 for survival." (PMID 34824248, 2021). "BCL2 and MYC are key targets of KMT2A-AFF1 and promote leukemia survival." (PMID 34088716, 2021). "In our study, p65 positively regulate FPGS transcription, and after inhibition of NF-κB activity by PDTC in Jurkat cells, the mRNA level of anti-apoptotic gene Bcl2 increased, implicating a pro-apoptotic role of NF-κB in the MTX induced apoptosis in leukemia cells." (PMID 32587478, 2020). "Some inhibitors such as entinostat, also known as MS-275, were also found to induce radical oxygen species (ROS) leading to cell death in leukemia cells through the regulation of BH3 interacting domain death agonist protein (Bid) and B-cell lymphoma-2 (Bcl-2) expression levels." (PMID 31248188, 2019). "Moreover, MLL-FPs are able to form a molecular complex with BRD4 (an epigenetic reader), PAFc and SEC to sustain the oncogenic expression of BCL2, CDK6, and MYC in MLL-r leukemias." (PMID 31157223, 2019). "After 6 hours of stimulation with IL-33, we observed significantly increased expression of Bcl-xl, TRAF-1, TRAF-2, and Mcl-1, but not Bcl-2 in leukemia cells." (PMID 30742053, 2019). "Venetoclax has been shown to inhibit growth of BCL-2 dependent leukemias without targeting platelets." (PMID 29854301, 2018). "The level of BAX mRNA and the BAX/Bcl-2 ratio in leukemia patient samples were not significantly different to the control group values." (PMID 29515335, 2018). "In comparison to normal B-cells, Eμ-Tcl1 Tg leukemias exhibited extensive Bcl-2 and Bcl-XL expression, with little or no expression of Mcl-1, Bfl-1/A1 or Bcl-w." (PMID 27843137, 2017). "For example, HL-60 cells of human leukemia subjected to the CAPE treatment revealed increased apoptosis by activation of different regulatory elements caspase-3 and BAX regulator and suppression Bcl-2." (PMID 28587155, 2017). "Small molecules that target Bcl-2 are used in the clinic to treat leukemia, but tight and selective inhibitors are not available for Bcl-2 paralog Bfl-1." (PMID 28594323, 2017). "Previous studies have shown that CDKIs (e.g., roscovitine) increase the lethality of the BH3-mimetic ABT-737, which inhibits Bcl-2/xL but not Mcl-1, in human leukemia cells." (PMID 28938651, 2017). "On comparison of our Capture-C data with CTCF ChIP-seq data (an ENCODE data set from K562 cells, ENCSR000DMA) that demarcates compartment boundaries, the major interaction site appears to be clustered at the 3′ end of BCL-2, thus marking a putative 3′ enhancer in MLL-AF4 leukemia cells." (PMID 27856324, 2017). "In HL-60 and K562 leukemia cell lines, up-regulation of Par-4 on treatment with arsenic contributes to induction of apoptosis, rather than down-regulation of Bcl-2." (PMID 29278364, 2017).
leukemia (continued). "Unlike other patient samples, leukemias containing the E2A-PBX1 fusion protein consistently exhibit BCL-2 expression levels similar to those of normal pre-B cells and lower than those of MLL-r and other leukemias." (PMID 27856324, 2017). "This residual activity was absent in Eμ-Tcl1 Tg leukemias over-expressing Bcl-2 derived from vav-Bcl-2 Tg Eμ-Tcl1 Tg mice." (PMID 27843137, 2017). "The reasons that MLLr samples are particularly addicted to BCL-2 are likely complex, but this current work suggests that there may be additional regulatory interactions on the protein level in MLL-AF4 leukemias." (PMID 27856324, 2017). "Indeed, throughout the years, other molecules and pathways, besides the HOXA9/MEIS pathway, have been postulated to play roles in the survival of MLL-r leukemia cells such as CMYC, BCL2 and the NFκB pathway." (PMID 27317766, 2016). "A similar mechanism for anti-leukemia activity of DS/Cu might also operate in vivo in PDX models of adult B-ALL, manifested by down-regulation of Bcl-2 and Bcl-xL after co-administration of DS/Cu." (PMID 27203215, 2016). "It has shown promising anti-leukaemia activity in patients whilst sparing platelets, suggesting that the megakaryocyte lineage does not require BCL-2." (PMID 25880088, 2015). "The growth inhibition of AML1−ETO+ leukemia cells induced by C646 are associated with the decreased acetylation of histone H3 and downregulation of Bcl2/C-kit, suggesting that C646 could be a promising drug candidate for the treatment of AML1−ETO+ leukemia." (PMID 26075180, 2015). "CD200 was more frequent in secondary compared to de novo leukemia (p = 0.0006), in CD34 positive cases (p = 0.00001), in Bcl2 overexpressing cases (p = 0.01), in those wild-type Flt3 (p = 0.004) and with favorable or unfavorable compared to intermediate karyotype (p = 0.0003)." (PMID 26338961, 2015). "Navitoclax is a first-in-class Bcl-2 inhibitor with demonstrated antitumor activity against SCLC solid tumor cell lines and hematologic malignancies such as chronic lymphocytic leukemia (CLL) and other leukemias." (PMID 25685063, 2015). "The re-initiation of leukemia was also significantly inhibited in absence of Inca1−/− in MLL—AF9- and c-myc/BCL2-positive leukemia mouse models." (PMID 25525809, 2014). "Interestingly, an inhibitor against both Bcl-2 and Bcl-X, ABT-737, displayed anti-leukemia effect on AML." (PMID 24952669, 2014). "The ratio of Bax: Bcl-2, rather than Bcl-2 alone, is important for the survival of drug-induced apoptosis in leukemia cell lines." (PMID 25531768, 2014). "Also in chronic myeloid (K562) and in acute lymphoblastic (HSB-2) leukemia cells, RSV induced cell growth inhibition and apoptosis through the increase of the pro-apoptotic Bcl-2 member Bax and the cytochrome c release." (PMID 24658441, 2014). "Previously, we have reported that sgRNA can be easily taken up by cultured cells without any transfection reagents, and naked sgRNAs targeting Bcl2 or WT1 mRNA can reduce their mRNA level and the amount of protein as well as inducing apoptosis in leukemia cells." (PMID 25437003, 2014). "Furthermore, deletion of Bcl-2 delayed the onset and reduced the severity of HoxA9/Meis1 and MLL-AF9 leukemias." (PMID 24177192, 2013). "Recent work has suggested that Bcl-2 overexpression defines a subset of OXPHOS-dependent, ROS-low, quiescent leukemia stem cells (LSC), in which pharmacologic or genetic inhibition of Bcl-2 rapidly diminishes oxygen consumption capacity and increases ROS generation prior to the onset of apoptosis." (PMID 23565503, 2013). "Half of them correspond to various phenotypes of cancer (e.g., leukemia, lung cancer and adrenal cortical carcinoma) based on the information retrieved from OMIM database, including several well-studied carcinogenesis genes (Bcl2, Casp8, Fas)." (PMID 24565050, 2013).
leukemia (continued). "The role of BCL-2 in tumorigenesis was further confirmed in Eμ-Myc/Eμ-Bcl-2 double transgenic mice where mice that overexpressed both MYC and BCL-2 became terminally ill from leukemia within 50 days while mice that solely expressed MYC required up to 100 days to succumb to malignancy." (PMID 23369605, 2013). "Treating TRAF2DN/Bcl-2 mice with empty liposomes had no significant impact on blood B cell counts or on the normal progression of the leukemia (8.2±1.4 vs 26.2±6.8 millions B cells/ml before and after the treatment, respectively)." (PMID 17593960, 2007). "The high expression of BCL2 and BAX suggests that this otherwise refractory subgroup might display a particular sensitivity to targeted therapy with BH3 mimetics, i.e. BCL-2 bound BAX might act as a suicide bag in this particular type of leukemia." (PMID 40234615, 2025). "By combining JAK2 inhibitors with other targeted therapies, such as inhibitors of BCL-2 (to promote apoptosis) or FLT3 inhibitors (to block additional tyrosine kinase signaling), it is possible to simultaneously target multiple signaling pathways that drive leukemia." (PMID 40486651, 2025). "By studying the ternary complex formation of VHL/753B and BCL2 or BCL-XL, it was possible to optimize the linker design and improve potency for both BCL-XL and BCL2 degradation, resulting in a highly promising compound that exhibited enhanced activity in leukemia cells." (PMID 40113751, 2025). "The transcriptional regulation of CDK6 and Bcl-2 (regulator proteins; block programmed cell death) influences the c-Myb transcription factor expression; thus, the CDK6 inhibitor may have an important influence on leukemia cells." (PMID 39598723, 2024). "In this work, we show that inhibiting MIF induces the death of leukemia cell lines and primary blasts and reprograms M2-like MΦ orientation when combined with GM-CSF, leading to blast cell death and reversal of resistance to therapies targeting FLT3-ITD or BCL-2 in vitro." (PMID 38548753, 2024). "Similarly, Bcl-2 overexpression is universally found in SLL, frequent in Mantle Cell Lymphoma and Waldenstrom Macroglobulinemia, and expressed in specific subsets of other leukemias and lymphomas." (PMID 38675444, 2024). "RM►GM-MΦ, while not fully reprogrammed, may affect response to BCL-2 inhibition in leukemia cells by changing their secreted cytokine profile or other mechanisms." (PMID 38548753, 2024). "Thus, As2 yields similar results in sensitizing leukemia cells to chemotherapy, as, for instance, small-molecule XIAP inhibitors that showed results against acute leukemia cells with Bcl-2-mediated resistance, synergizing with TRAIL (TNF-related apoptosis-inducing ligand) or Fas activation." (PMID 38731935, 2024). "However, the anti-leukemia activity of DZNeP in combination with BCL-2 inhibitors has not been reported so far." (PMID 36232694, 2022). "However, the role of c-KIT in leukemia stem cells (LSCs) and the BCL-2 inhibitor resistance is not well explored." (PMID 36232694, 2022). "The first generation BCL-2 inhibitor ABT-737 induced apoptosis in AML-derived cell lines, in primary blasts, and in phenotypically defined AML stem cells; inhibited the growth of clonogenic AML progenitor cells; and was effective in reducing the leukemia burden in vivo in mice models of AML." (PMID 34830763, 2021). "Overexpression of MCL1 and/or BCLXL may play a major role in the pathogenesis of various types of leukemia and mediate venetoclax resistance if BCL2 overexpression is not the primary antiapoptotic driver." (PMID 33796823, 2021). "Full transformation associates with transcriptional upregulation of oncogenes such as Myc or Bcl2, downregulation of tumor suppressors such as Ikzf1 or Arid2, and major IL-7R signaling upregulation (involving JAK/STAT5 and PI3K/mTOR), required for leukemia cell viability." (PMID 34907175, 2021).